RHOC (ras homolog family member C)
Diseases named in the same sentence as RHOC in open-access papers (continued):
Sharing a sentence is not in itself a finding about the gene and the disease.
head and neck squamous cell carcinoma (6 papers, 2014 to 2021). A squamous cell carcinoma that arises from any of the following anatomic sites: lip and oral cavity, nasal cavity, paranasal sinuses, pharynx, larynx, and salivary glands. "RhoC knockdown in HNSCC (Head and Neck Squamous Cell Carcinoma) showed a defect in activation of STAT3 in the cells and therefore a reduction in the expression of core stem cell markers like Oct3/4, Sox2, and Nanog." (PMID 27597870, 2016). "In this study we investigated the correlation between RhoC expression and cancer stem cells (CSCs) formation in head and neck squamous cell carcinoma (HNSCC)." (PMID 24533098, 2014). "Two studies have demonstrated that miR-138 inhibits the migration and invasion of tongue squamous cell carcinoma (TSCC) and head and neck squamous cell carcinoma (HNSCC) cells, respectively, by targeting RhoC mRNA." (PMID 34627249, 2021). "RhoC expression is found to be correlated to CSC formation in head and neck squamous cell carcinoma (HNSCC)." (PMID 26631279, 2015).
metastatic tumors (6 papers, 2005 to 2025). "Since RhoC is one of the few antigens which has been shown to be expressed in metastatic disease, we propose that targeting this protein by vaccination should be combined, e.g., with checkpoint inhibitor therapy, to increase clinical efficacy." (PMID 40333248, 2025). "RhoC, a member of the Ras homologous gene family C (RhoC), demonstrates increased expression levels in advanced solid tumors, metastatic tumors, and cancer stem cells." (PMID 40145100, 2025). "It has been shown that its expression in non-metastatic disease induces cell invasion and metastasis, probably by increasing the expression of RhoC (Ras homolog gene family, member C), a known oncogene." (PMID 31979244, 2020). "It seems to be a promising cure for the metastatic tumors to develop small molecule inhibitors for RNF180 to target RNF180-decreased RhoC." (PMID 33082325, 2020). "Given the role of RhoC in cellular migration and its prevalence in metastatic tumors, it was a logical choice to examine in relationship to cav-1." (PMID 15969750, 2005). "Additionally, the metastatic tumor area was reduced in the superficial cervical lymph nodes in the RhoC/shRNA group." (PMID 33519932, 2021). "RhoC GTPase is prevalent in metastatic tumors, particularly in PC." (PMID 15969750, 2005).
head and neck cancer (4 papers, 2009 to 2021). A primary or metastatic malignant neoplasm affecting the head and neck. "Moreover, reconstitution of constitutive active RhoA or RhoC in these PKCε-deficient head and neck cancer cells rescued the loss-of-function motility defect providing direct evidence that RhoA and RhoC is downstream of the PKCε signaling cascade." (PMID 19228372, 2009). "Atorvastatin-mediated inhibition of RhoC also blocked metastasis in head and neck cancer cells, in vitro." (PMID 31340863, 2019). "In the present study, we investigated the role of RhoC in head and neck cancer stem cell formation and the mechanism of activation of CSC transcription factors." (PMID 24533098, 2014). "One of the most basic clinical questions that we addressed at this point is how the knocking down of RhoC function affects tumor cells with stem cell-like properties in head and neck cancer." (PMID 24533098, 2014). "We then used these stable clones to elucidate the effect of RhoC inhibition on the head and neck cancer cell population that exhibits stem cell-like features." (PMID 24533098, 2014). "In our current study we show a significant decrease in the ALDH positive cells in the RhoC knockdown head and neck cancer cell lines." (PMID 24533098, 2014). "Furthermore, we have also shown CD44 (another stem cell surface marker) expressing cells decrease in the RhoC depleted head and neck cancer cell lines." (PMID 24533098, 2014). "Based on our findings, we constructed the signaling pathway by which RhoC regulates CSC growth and self-renewal in head and neck cancer." (PMID 24533098, 2014).
invasive breast carcinoma (4 papers, 2014 to 2023). A carcinoma that infiltrates the breast parenchyma. "RhoC plays an important role in tumor metastasis and is considered a biomarker for invasive breast cancer." (PMID 24587105, 2014). "Additionally, COMMD4_AS1, GNAS, POLDIP3, FASTK, and RHOC AS were significantly associated with METTL3 deletion whereas AS of EXOC7 correlated with both deletion and gain of METTL3 in invasive breast carcinoma." (PMID 36725888, 2023). "In support of this, RhoC protein was found to be exclusively expressed in invasive breast carcinomas and not in normal breast, atypical intraductal hyperplasia or ductal carcinoma in situ, and increased levels of RhoC protein positively correlated with node-positive tumors." (PMID 32992837, 2020).
non-small cell lung carcinoma (4 papers, 2010 to 2019). A group of at least three distinct histological types of lung cancer, including non-small cell squamous cell carcinoma, adenocarcinoma, and large cell carcinoma. "Proteomic studies have revealed that RhoC is overexpressed in etoposide chemo-resistant non-small cell lung cancer." (PMID 31488179, 2019). "The aim of this study is to investigate the expressions of PRL-3 and RhoC proteins and their correlation to invasion and metastasis of non-small cell lung cancer (NSCLC), which may provide experiment evidence of the mechanism of PRL-3 in tumorigenesis and tumor-development." (PMID 20681446, 2010). "A recent report implicates RhoC in chemoresistance in non-small cell lung cancer, however its role in radioresistance is not elucidated in any tumor model." (PMID 31488179, 2019).
pancreatic adenocarcinoma (4 papers, 1998 to 2019). "Overexpression of the rhoC gene significantly correlated with poorer prognosis of patients with pancreatic adenocarcinoma (P < 0.05)." (PMID 9459160, 1998). "Analysis of the pancreatic adenocarcinoma (PDA) TCGA dataset revealed a correlation between elevated RhoA, RhoC and MRTF expression and decreased survival in PDA patients." (PMID 31068602, 2019).
ductal adenocarcinoma of the pancreas (3 papers, 1998 to 2011). "Moreover, increased expression of RhoC correlates with the progression and poor prognosis of ductal adenocarcinoma of the pancreas." (PMID 22016776, 2011).
endometrial carcinoma (3 papers, 2016 to 2019). A malignant tumor arising from the epithelium that lines the cavity of the uterine body. "Taken together, these results demonstrate that miR-372 inhibits the tumorigenesis and development of endometrial cancer by targeting RhoC through the regulation of a series of relevant genes." (PMID 26673619, 2016). "Furthermore, as a lncRNA, TDRG1 enhanced tumorigenicity by inhibiting the miR-93/RhoC pathway in epithelial ovarian carcinoma and promoted endometrial carcinoma cell development and invasion by positively targeting VEGF-A in endometrial carcinoma." (PMID 31164797, 2019). "Interestingly, we found another target of miR-372 in endometrial carcinoma, namely RhoC, which is involved in the tumorigenesis and development of many kinds of malignant tumors in humans." (PMID 26673619, 2016). "RhoC expression was not significantly different after the endometrial carcinoma cells had been transfected with miR-93." (PMID 27829043, 2016). "Therefore, the miR-372/RhoC pathway and the miR-372/Cyclin A1 and CDK2 pathway may collectively be involved in the anti-oncogenic properties of miR-372 in endometrial carcinoma." (PMID 26673619, 2016).
invasive carcinoma (3 papers, 2014 to 2017). A carcinoma that is not confined to the epithelium, and has spread to the surrounding stroma. "Although very few genetic mutations are observed in the RhoC gene, it is reported to be over-expressed in many forms of invasive carcinomas including HNSCC." (PMID 24533098, 2014). "The prevalence of RhoC in a wide range of invasive carcinomas and its function as a signaling GTPase suggests it can regulate other pathways which are involved in the transformation of tumor cells into a metastatic phenotype." (PMID 24533098, 2014). "To unravel the contribution of RhoA and RhoC during the development of non-transformed breast epithelial cells to invasive carcinoma, we established stable MCF-10A cell lines, in which expression of RhoA or RhoC can be induced by doxycycline." (PMID 29152087, 2017).
lung adenocarcinoma (3 papers, 2017 to 2024). A carcinoma that arises from the lung and is characterized by the presence of malignant glandular epithelial cells. "Similarly, RNF168 was shown to be lowly expressed in lung adenocarcinoma tissues and promote the degradation of RHOC protein by ubiquitinating RHOC, thus suppressing the cancer stem cell (CSC)-like traits of non-small cell lung cancer (NSCLC) cells." (PMID 36771081, 2023).
Myocardial fibrosis (3 papers, 2021 to 2025). "In M2 macrophage-derived small extracellular vesicles (SEVs), circUbe3a promotes myocardial fibrosis by targeting the microRNA-138-5p/RhoC axis, driving cardiac fibroblast proliferation, migration, and phenotypic transformation, thereby worsening myocardial fibrosis after MI560." (PMID 40404619, 2025). "Exacerbates MI-induced myocardial fibrosis via miR-138-5p/RhoC axis." (PMID 36768449, 2023).
oral cancer (3 papers, 2021 to 2022). "The expression of RhoC in oral cancer was analyzed in datasets from TCGA." (PMID 33519932, 2021). "MMP-9 knockdown inhibits oral cancer cell invasion and metastasis not only by inhibiting OSCC cell proliferation, migration, and vascular endothelial cell adhesion and angiogenesis but also by inhibiting other tumor metastasis-related factors, such as RhoC and Src genes." (PMID 33828938, 2021).
cholangiocarcinoma (2 papers, 2017 to 2024). A carcinoma that arises from the intrahepatic biliary tree (intrahepatic cholangiocarcinoma) or from the junction, or adjacent to the junction, of the right and left hepatic ducts (hilar cholangiocarcinoma). "RHOC has been shown to promote the malignant progression of cholangiocellular carcinoma cells via the regulation of MMP 2, 3, and 9 expression levels." (PMID 39066215, 2024). "For instance, downregulation of miR-138 promoted the malignant progression in cholangiocarcinoma by its target RhoC (ras homolog gene family, member C)." (PMID 29147648, 2017).
colorectal tumor (2 papers, 2009 to 2010). "Recombinant adenovirus mediated RhoA and RhoC shRNA in tandem linked expression may inhibit the growth of human colorectal tumor xenografts in vivo." (PMID 20828398, 2010).
diabetic retinopathy (2 papers, 2024). "have pinpointed six significant genes (CD44, CDC42, TIMP1, BMP7, RHOC, FLT1) as crucial for diabetic retinopathy through advanced bioinformatics analysis coupled with in vivo validation." (PMID 38605967, 2024).
endometriosis (2 papers, 2020 to 2025). The growth of functional endometrial tissue in anatomic sites outside the uterine body. "Other report considered the increased RhoC expression detected in endometriotic lesions might be among the key elements involved in the origin and the maintenance of endometriosis." (PMID 32725958, 2020). "It is reported that RhoA, RhoC and ROCK1 were significantly higher in ectopic endometrial cells compared with the eutopic endometrial cells in endometriosis, which involved with promoted migration of endometrial cells of endometriosis." (PMID 32725958, 2020). "Additionally, the protein expression levels of RhoA, RhoC, and ROCK were markedly reduced in the miR-183 mimic group, indicating that miR-183 markedly inhibited the expression of RhoA, RhoC, and ROCK proteins in endometriosis." (PMID 40630207, 2025).
lymph node metastasis (2 papers, 2019 to 2021). "It has been reported that RhoC overexpression may predict lymph node metastasis and poor prognosis." (PMID 33828938, 2021).
mammary adenocarcinoma (2 papers, 2015 to 2016). "A specific role for RhoC has also been demonstrated in a mouse mammary adenocarcinoma model in which RhoC depletion abolished occurrence of lung metastasis." (PMID 27487152, 2016).
metastatic cancer (2 papers, 2014 to 2020). A carcinoma which has spread from the original site of growth to another anatomic site. "Over-expressed RhoC is one of the established hallmarks for aggressive and metastatic cancers." (PMID 24533098, 2014).
metastatic melanoma (2 papers, 2009 to 2021). A melanoma that has spread from its primary site to another anatomic site. "Gene expression analyses of metastatic melanoma have consistently identified RhoC as a major component of metastatic melanoma in vivo." (PMID 19400942, 2009). "CYT-high metastatic melanomas had recurrent copy number amplifications in loci 1p12 (NOTCH2), 1q44 (OR2M4), 7q36.1 (KCNH2), 11q13.3 (FGF3/4), 12p11.23 (MED21) and 12q13.3 (R3HDM2) and deletions in 1p22.1 (RHOC, NRAS), 9p21.3 (CDKN2B), 10q23.2 (miR346), 11q23.3 (ATM, CHEK1, ETS1) and 15q15.3 (CASC4)." (PMID 33779796, 2021).
neuroblastoma (2 papers, 2010 to 2018). Neuroblastoma (NB) is the most common solid, extracranial childhood tumor. "Products of other genes, i.e., RHOC, RHOA, CCT5 and TUFM, were reported as also being involved in cytoskeleton rearrangements that are necessary for changes of cell morphology during the neuronal differentiation of neuroblastoma cells." (PMID 20459794, 2010).
tongue SCC (2 papers, 2017 to 2020). "RhoC expression were reduced in tongue SCC cells transfected with ectopic miR-138, and led cells to and changed morphology and increased cell migration and invasion." (PMID 31983155, 2020).
adenoma (1 paper, 2015). A neoplasm arising from the epithelium. "We found that RhoA-null adenomas maintained or upregulated pMLCSer19 signaling, suggesting likely compensation by RhoC or other related Rho GTPases." (PMID 26030593, 2015). "Taken together, these results indicate that while RhoA and RhoC are each dispensable for K-RasG12D mediated tumorigenesis, together they contribute to adenoma formation." (PMID 26030593, 2015). "Rather, deletion of RhoA alone exacerbated lung adenoma formation, whereas dual deletion of RhoA and RhoC together significantly reduced K-RasG12D induced adenoma formation." (PMID 26030593, 2015). "The interplay between RhoA and RhoC signaling is in some ways similar to that of B-Raf and c-Raf in oncogenic K-Ras-driven adenoma initiation." (PMID 26030593, 2015). "We found that all adenomas in the RhoWT, RhoC-/- and DKO groups expressed RhoA in the Adeno-Cre induction model." (PMID 26030593, 2015). "Fifth, an attempt at combined deletion of RhoA and RhoC resulted in reduced adenoma formation and retention of RhoA in all adenomas." (PMID 26030593, 2015). "Hematoxylin and eosin (H&E) staining demonstrated adenoma formation in RhoWT, RhoAcKO, RhoC-/- and DKO mice." (PMID 26030593, 2015). "We crossed RhoAflox/flox;RhoC-/- mice with the CCSP-Cre;LSL-K-RasG12D line and observed adenoma formation in both RhoC-/- and DKO mice." (PMID 26030593, 2015). "Additionally, immunohistochemistry for RhoA showed that almost all adenomas in the RhoC-/- and DKO stained positively for RhoA." (PMID 26030593, 2015). "We further assessed whether double deletion of RhoA and RhoC would affect K-RasG12D induced adenoma formation." (PMID 26030593, 2015). "However, DKO mice had fewer adenomas and these tumors were smaller than those formed in either RhoWT or RhoC-/- mice." (PMID 26030593, 2015). "Immunohistochemical staining revealed positive RhoA staining in all adenomas from the RhoWT, RhoC-/- and DKO groups, whereas only a subset of adenomas from the RhoAcKO group expressed RhoA." (PMID 26030593, 2015). "Consistent with this interpretation, the phosphorylation status of MLC, downstream of RhoA and RhoC signaling, was not decreased in either RhoA or RhoC-null adenomas, nor in adenomas from DKO mice, in which RhoA is retained." (PMID 26030593, 2015).
Alzheimer disease (1 paper, 2022). A progressive, neurodegenerative disease characterized by loss of function and death of nerve cells in several areas of the brain leading to loss of cognitive function such as memory and language. "Another study has shown that miR-20b-5p, via targeting RhoC gene, could disturb progression of Alzheimer’s’ disease by regulating the cell apoptosis, and cell viability." (PMID 36582800, 2022).
bladder tumor (1 paper, 2021). "MiR-491-3p was also reported to directly target RhoC and FZD4 to suppress bladder tumor cell mobility." (PMID 33098307, 2021).
cervical squamous cell carcinoma (1 paper, 2020). A squamous cell carcinoma arising from the cervical epithelium.
cervical tumour (1 paper, 2010). "As both Notch1 and RhoC are involved in tumour progression and metastasis, we investigated whether the two signalling molecules regulate similar functions during cervical tumour progression." (PMID 19953094, 2010). "We thus propose RhoC to be a downstream effector of Notch1 in cervical tumour progression." (PMID 19953094, 2010).
Cirrhosis (1 paper, 2019). A chronic disorder of the liver in which liver tissue becomes scarred and is partially replaced by regenerative nodules and fibrotic tissue resulting in loss of liver function. "A univariate Cox regression analysis was applied to identify important prognostic factors of recurrence-free survival, which tested parameters including age, gender, HBsAg status, cirrhosis, tumor size, TNM stage and Pin1/RhoA/RhoC co-expressions." (PMID 31324164, 2019).
ductal breast carcinomas (1 paper, 2017). "RhoC was expressed in all evaluated matched normal epithelia, DCIS and ductal breast carcinomas." (PMID 29152087, 2017).
gastric tumors (1 paper, 2015). "miR-10b can stimulate the upregulation of RhoC and AKT phosphorylation through targeting HOXD10, thus promoting cell invasion in gastric tumors." (PMID 26311318, 2015).
glaucoma (1 paper, 2022). Increased pressure in the eyeball due to obstruction of the outflow of aqueous humor. "For example, CDCA8, HLA-B, RHOC, PPM1J, RPL10A, and TEAD3 are associated with glaucoma (P < 1 × 10−6)." (PMID 36450729, 2022).
immune deficiency (1 paper, 2024). "The GSEA analysis unveiled TFRC involvement in regulating the malignant phenotype of CC, as well as its participation in pathways linked to immune deficiency, the JNK pathway, chromosome condensation, the RHOC GTPase cycle, and ECM receptor interactions associated with invasive functions." (PMID 39131609, 2024).
leukemia (1 paper, 2023). A malignant (clonal) hematologic disorder, involving hematopoietic stem cells and characterized by the presence of primitive or atypical myeloid or lymphoid cells in the bone marrow and the blood. "Therefore, appropriate systems that could deliver RhoA/RhoC siRNAs to leukemia cells in a safe manner are significant for clinical application in leukemia therapy." (PMID 36674556, 2023).
Lissencephaly (1 paper, 2022). A spectrum of malformations of cortical development caused by insufficient neuronal migration that subsumes the terms agyria, pachygyria and subcortical band heterotopia. "The data suggest that pathological activation of LNX1 and RhoC contributions to a lissencephaly phenotype may be the consequence of reduced LIS1 protein levels rather than missense-dependent disruption of LNX1-LIS1 specific binding." (PMID 36192543, 2022).
liver cancer (1 paper, 2023). An epithelial or non-epithelial malignant neoplasm that arises from the liver. "Their insights into the mechanism revealed FOXM1’s role in promoting liver cancer cell invasion and metastasis by upregulating MMP-7, RhoC, and ROCK1, with HBx further amplifying FOXM1 expression through the ERK/CREB pathway." (PMID 37817774, 2023).